FGF2 (fibroblast growth factor 2)
Diseases named in the same sentence as FGF2 in open-access papers (continued):
Sharing a sentence is not in itself a finding about the gene and the disease.
tumor (continued). "The increased activities of autocrine and paracrine loops in human malignancies also play an important regulatory role in their pathogenesis due to the well-known abilities of FGFR ligands, especially FGF-2, to regulate angiogenesis and promote tumor growth, invasiveness, and disease progression." (PMID 32599808, 2020). "Unexpectedly, anti-PDGFRβ alone treatment augmented tumor angiogenesis in FGF-2+ tumors." (PMID 32709869, 2020). "Collectively, these results demonstrate that miR‐646 acts as a tumor suppressor in NSCLC by targeting FGF2 and CCND2, and may serve as a therapeutic target for patients with NSCLC." (PMID 32347652, 2020). "bFGF—also called FGF2—was discovered first, and plays a crucial role in tumor angiogenesis." (PMID 32993787, 2020). "Therefore, we took the top 20 genes in Degree and the tumor-associated pathway-related gene to take Venn intersection, and identified three Hub genes: PDGFRB, KDR and FGF2." (PMID 32011476, 2020). "Of note, IM-induced activation of the FGF-2/FGFR loop in GIST might be a factor mediating tumor resistance to IM." (PMID 32599808, 2020). "In addition, Xiao and colleagues reported that TGF‐β‐induced EndMT was modulated by FGF2 secreted from TECs isolated from tumor tissues formed in the transgenic mouse models." (PMID 31094056, 2019). "Our data suggest that TGF‐β and FGF2 oppose and cooperate with each other during the formation of myofibroblastic and non‐myofibroblastic cells from TECs, which in turn determines the characteristics of mesenchymal cells in the tumor microenvironment." (PMID 31094056, 2019). "FGF2 is a proangiogenic factor involved in tumor angiogenesis, invasion and migration." (PMID 31035725, 2019). "In addition to affecting the VEGF signaling complexes, release of PF4 influences the FGF2 signaling complexes to different extents, depending on the tumor microenvironment." (PMID 31379588, 2019). "It suppressed the growth of OSCC tumor through the targeting of FGF2." (PMID 31462890, 2019). "Additionally, the tumor microenvironment promotes the tumor-associated type II macrophage differentiation, which will release high amounts of VEGF, PDGF, FGF-2, MMPs, TNF, and inducible nitric oxide synthase-released reactive oxygen species." (PMID 31905724, 2019). "Collectively, these data indicate that FGF2 secreted by ASCs acts in a paracrine fashion on FGFR1-expressing chemo-residual TNBC cells to activate ERK signaling, which is associated with an increase in tumor cell proliferation." (PMID 30594967, 2019). "Moreover, by cooperating with proinflammatory cytokines, FGF2 can also promote the expression of adhesion molecules by endothelial cells, thus contributing to the recruitment of circulating immune cells to the tumor." (PMID 31681612, 2019). "The present study, for the first time, demonstrated that TGF‐β and FGF2 oppose and cooperate with each other during the formation of various types of mesenchymal cells from TECs, which contributes to the characteristics of tumor microenvironment." (PMID 31094056, 2019). "This suggests that palladium containing HANPs downregulate FGF2 expression in our tumor model." (PMID 30824801, 2019). "Besides, PDGF, TGF- β, and FGF-2, together with vascular endothelia growth factor (VEGFR) secreted by fibroblasts and tumor associated macrophages, promote the angiogenesis, lymphangiogenesis, and lymphovascular invasion." (PMID 31741805, 2019). "An FGF2-neutralizing antibody inhibited ASC-induced chemo-residual tumor cell proliferation." (PMID 30594967, 2019). "Therefore, the T-to-NT ratio was calculated and as a result we observed higher expression of PROX1 in three tumor cases (case number: 42, 149 and 157), whereas FGF2 expression revealed opposite pattern." (PMID 31717665, 2019). "However, a PDGFRβ specific neutralizing antibody almost completely ablated the pericytes from tumor tissues, indicating that the PDGFRβ receptor signaling is involved in FGF-2-induced pericyte recruitment." (PMID 29423271, 2018).
tumor (continued). "Usually, the biological effect exerted by FGF2 on ECs is the consequence of a paracrine stimulation due to its release by inflammatory cells, stromal components or tumor cells, as well as by its mobilization from FGF-binding components that are present in the extracellular matrix (ECM)." (PMID 30349543, 2018). "This suggests that the inhibitory effect of honokiol on tumor xenograft growth may be related to the downregulation of FGF2 and the inhibition of FGFR1." (PMID 30515999, 2018). "In addition, Malat1 was reported to play an important role in tumor-driven angiogenesis through regulating vasculature formation and fibroblast growth factor 2 expression." (PMID 29891768, 2018). "Similarly, imatinib also significantly blocked FGF-2-induced pericyte proliferation in the in vivo tumor models." (PMID 29423271, 2018). "Indeed, we have found that FGF-2-expressing tumors show improvement of blood perfusion, which would be translated into an accelerated tumor growth rate." (PMID 29423271, 2018). "In turn, the tumor cells themselves produce cytokines, such as fibroblast growth factor 2 (FGF-2) and platelet derived growth factor (PDGF), to continuously recruit more fibroblasts, and then these fibroblasts generate even greater amounts of HGF, thus contributing to the growth of the tumor mass." (PMID 29342862, 2018). "Increased VEGF and FGF2 expression and accumulation were identified in the tumor microenvironment." (PMID 30285793, 2018). "This biphasic effect of FGF2 might be one of the mechanisms utilized by cancer cells to escape from host immune reactions during the angiogenic stage of tumor development." (PMID 30349543, 2018). "Additionally, PERK-mediated upregulation of vascular endothelial growth factor (VEGF), fibroblast growth factor 2 (FGF2), and interleukin-6 (IL-6), and downregulation of anti-angiogenic cytokines remarkably facilitate tumor growth." (PMID 30282948, 2018). "FGF2 is a pleiotropic growth factor involved in embryonic development, wound healing, angiogenesis, and tumor progression, but whether CEP57 is important for any of these biological functions is unclear." (PMID 30035751, 2018). "FGF2 expression increased during tumor progression from normal to cancer states (P<0.01)." (PMID 28092370, 2017). "Notably, a larger tumor size of cervical neoplasia had a significant correlation with triple-positive API5+/FGF2+/NANOG+ expression." (PMID 28092370, 2017). "In addition, neutrophils promote tumor angiogenesis through the release of angiogenic factors, such as vascular endothelial growth factor, angiopoietin-1, and fibroblast growth factor-2." (PMID 28321405, 2017). "However, the infection of CAFs was found to lead to enhanced secretion of fibroblast growth factor 2 (FGF2) leading in turn to impaired evasion of tumour cells to OV infection." (PMID 29157300, 2017). "Importantly, NCAN, as a component of extracellular matrix, is reported to bind to HSPGs including glypican-1 and syndecan-3 and FGF2 via its C-terminal domain, which was shown to be essential for tumor sphere formation in our experiments." (PMID 29290949, 2017). "GL261 cells were obtained from the NCI-Frederick Cancer Research Tumor Repository and cultured as adherent cells or induced to form neurospheres by placing freshly trypsinized cells into serum-free media containing fibroblast growth factor 2, epidermal growth factor, and B-27 supplement." (PMID 28768483, 2017). "MiR-503 inhibited tumor angiogenesis in HCC by targeting FGF2 and VEGFA." (PMID 28740507, 2017). "Moreover, the finding that shRNA knockdown of GPC1 removes ability of FGF2 to rescue KO/PyMT proliferation to WT/PyMT levels, indicates the difference in sensitivity to FGF2 signalling between KO/PyMT and WT/PyMT tumour cells to depend on GPC1." (PMID 28102194, 2017). "Moreover, FGF2 is believed to play a role in cancer, both by stimulating angiogenesis and tumor cells growth directly." (PMID 27506449, 2016).
tumor (continued). "In addition, fibroblasts within tumor stroma can be activated by FGF2 secreted from endothelial and tumor cells." (PMID 27007053, 2016). "However, high serum FGF2 levels were significantly correlated with tumor bulkiness in Non-Hodgkin's lymphoma (NHL)." (PMID 27007053, 2016). "Several studies have shown that FGF2 is a key tumor-promoting factor in the tumor microenvironment." (PMID 27007053, 2016). "FGF2 secreted by stromal fibroblasts induces tumor cell proliferation via FGFR paracrine signaling." (PMID 27007053, 2016). "FGF binding protein (FGF-BP) is secreted by multiple tumours and can liberate FGF2 from the ECM." (PMID 26620208, 2016). "Recently, FGF2 was demonstrated to promote tumor cell proliferation, migration, and invasion." (PMID 26655091, 2016). "Furthermore, an immunohistochemical analysis demonstrated that the number of FGF2-positive cells to significantly increase in bevacizumab-treated tumours compared with the control-treated tumours on day 28 after tumour cell inoculation." (PMID 26635184, 2015). "We next examined what type of cells expressed FGF2 in the bevacizumab-resistant tumour environment." (PMID 26635184, 2015). "We further investigated whether FGF2 over-expression could attenuate the tumor suppressive effects of miR-203." (PMID 25890121, 2015). "Together with the results from mouse models, these findings indicate that fibrocyte-like cells may be key regulatory cells in the tumour microenvironment that are involved in the acquisition of resistance to anti-VEGF therapy through their production of FGF2." (PMID 26635184, 2015). "Tumor derived FGF-2 may promote cancer progression by elevating proteolytic enzymes and by paracrine stimulation of vascular endothelial cell growth." (PMID 26465941, 2015). "To confirm the results from immuonofluorescence and flow cytometry indicating that the number of fibrocyte-like cells was increased and that these were the FGF2-producing cells in the bevacizumab-resistant tumours, we isolated and characterized the fibrocyte-like cells from mouse tumour tissue." (PMID 26635184, 2015). "Thus, FGF2-T-MAE cells represent an interesting model of FGF2-driven tumor development and for assessing the efficacy of anti-FGF2 therapeutic approaches." (PMID 25609197, 2015). "Recent studies indicated that FGF2 was an important proangiogenic growth factor that stimulated the growth, survival and migration of endothelial cells, and promotes the development and tumour angiogenesis." (PMID 25890121, 2015). "Moreover, accumulating evidence indicates that FGF2 is involved in resistance of tumor vascularization against VEGF inhibitor treatment." (PMID 25609197, 2015). "Indeed, our data demonstrate the capacity of the compound to affect also single cell survival of FGF2-dependent 3F2T.luc2 tumor cells and their capacity to induce lung metastases following i.v. injection in immunocompromised animals." (PMID 25609197, 2015). "In addition, it was also confirmed that FGF2 was predominantly produced by GFP-positive cells in bevacizumab-resistant tumour in bone marrow chimeric mice." (PMID 26635184, 2015). "In addition, the number of FGF2-expressing cells was also significantly increased in the tumours from patients who received bevacizumab-containing chemotherapy." (PMID 26635184, 2015). "In addition, FGF2 promotes tumor progression and previous studies indicate that the upregulation of FGF2 is important in prostate carcinogenesis and malignant progression." (PMID 24959249, 2014). "It is of interest to note that as intimated in the PDAC setting, the tumor type, the Sulf isoform (Sulf1 and/or Sulf2), and the predominant pathway (Wnt or FGF2) might result in opposing effects of Sulf’s on tumor progression and metastasis." (PMID 25105093, 2014). "In the tumor, FGF2 is secreted by stromal fibroblasts as part of the microenvironment and may serve either as a stem-cell maintaining or differentiating factor." (PMID 24799129, 2014).
tumor (continued). "Mast cells can exert pro-tumorigenic effects by secreting factors like VEGF, angiopoietin-1, CXCL1, and IL-8 that promote tumor angiogenesis, as well as growth factors such as PDGF, NGF, SCF, FGF2, and proteases that facilitate tumor cell growth and metastases." (PMID 24455486, 2014). "ECM1 is known to interact with the EGF domain on other proteins, such as perlecan, and perlecan may induce heparin-binding growth factor responses, including the fibroblast growth factor 2 (FGF2) response, and thereby promote tumor growth." (PMID 25499743, 2014). "However, some miRs such as miR-503 downregulated by HIF-1α inhibit tumor angiogenesis by targeting FGF2 and VEGF." (PMID 24914051, 2014). "It is possible that opposite effects were FGF-dependent (FGF2 for the oncogenic effect and FGF9 for the tumor suppressive effect), the role of FGF2 being supported by previous studies (for example) but more work is needed to test the dependency of FGFR3 to FGFs." (PMID 23902722, 2013). "In parallel, upon RUNX2 knockdown, we have observed a predominant and strong downregulation of gene nodes known to be implicated in EOC tumorigenesis (PTGS1/COX1, FGF2, IL1A, Sapk, C/ebp, SELE, UBQLN1, PSAT1, ALDH1A1, GDF15, MTHFD2), including EOC tumor invasion/metastasis (MMP1, MMP13, Creb);." (PMID 24124450, 2013). "In addition, FGF2 can also act as an antiapoptotic factor, rendering tumor cells more resistant to chemotherapy." (PMID 23991123, 2013). "Similarly, in multiple basal-like breast cancer cells, tumor growth was suppressed following RNAi-mediated silencing of endogenous FGF2." (PMID 23900974, 2013). "GPC3 modulates the effect of growth factors such as IGF-2, BMP-7 and FGF-2 on hepatoma cells and may recruit M2 tumor-promoting macrophages to the HCC microenvironment." (PMID 22564378, 2012). "The angiogenic factors VEGFA and FGF2 directly promote tumor angiogenesis." (PMID 22895562, 2012). "Moreover, extracellular FGF2 expression contributes to radio- and chemotherapy resistance in multiple tumour types, further validating the importance of the tumour cell microenvironment in tumorigenesis." (PMID 21197469, 2011). "FGF2/FGFR-1 expression was localized in the cytoplasm of tumor cells." (PMID 21733164, 2011). "In the study presented herein we have observed high tumor expression of FGF2 and the co-expressions of FGF2 & PDGF-B and FGF2 & VEGFR-3 to be significant, independent and unfavorable prognostic indicators of DSS in non-GIST STS patients with wide resection margins." (PMID 21733164, 2011). "We also assessed whether the stem cell culture cytokines EGF and FGF-2 contribute to differences between stem-like and more differentiated tumor cells in terms of DNA damage levels and of apoptosis resistance upon γ-irradiation." (PMID 21663643, 2011). "It has been hypothesized that during wound healing and tumor development the action of heparan sulfate degrading enzymes activates FGF2, thus mediating the formation of new blood vessels." (PMID 21483670, 2011). "FGF2 protein levels have been reported to be significantly increased in BC tissues, and its expression is positively correlated with tumor grade." (PMID 21483670, 2011). "It is also worth noting that FGF-2 participates in tumor angiogenesis." (PMID 24212642, 2011). "We can speculate that FGF-2 from CAF-HI might be contributing to the development of a pro-angiogenic milieu creating a permissive microenvironment that favors tumor growth." (PMID 20553594, 2010). "Moreover, since FGF-2 is not only an angiogenic factor, but also a major promoter of tumor cell malignant behavior, the possibility exists that TSP-1, DD15 and sm27 have a direct anti-invasive and anti-metastatic activity, that warrants further investigation." (PMID 21317461, 2010).
tumor (continued). "This study proved the benefit of the FGF2-targeting system, which has high transduction efficiency and enables a lower titre viral administration while still maintaining in vitro and in vivo tumour suppressive effect of cisplatin equivalent to a higher titre non-targeting transfer." (PMID 21063405, 2010). "The same mouse model was used to further evaluate whether the in vitro transduction efficiency and cytotoxicity after FGF2-targeted Ad-NBS1 gene transfer translated into a beneficial effect on in vivo tumour growth." (PMID 21063405, 2010). "In this study, we wanted to reproduce these in vitro findings in an in vivo setting and we hypothesized that CAF-HI, by secreting FGF-2 or other paracrine factors, would be able to promote the growth of HD tumor cells." (PMID 20553594, 2010). "Another study indicated that FGF-2 could directly upregulate MMP-7 gene expression in human tumor cell lines and umbilical vein endothelial cells through AP-1 and STAT3." (PMID 20939893, 2010). "Downregulation of both Ras/MEK pathway and PI3K/AKT pathway may have synergistic effects in inducing tumour angiogenesis, and with NF-κB downregulation, a potent inhibition of tumour angiogenesis can be expected after FGF2-targeted Ad-NBS1 transduction." (PMID 21063405, 2010). "FGF2 seems to stimulate both tumor cell growth and angiogenesis through paracrine mechanisms." (PMID 19126230, 2009). "FGF-2 is a pro-mitogenic growth factor located in basement membranes and in the subendothelial extracellular matrix of blood vessels and is involved in wound healing, tumor formation, and angiogenesis." (PMID 18698376, 2008). "However they also point to the complexity of the cellular response to hypoxia, and incite us to decipher more deeply the mechanisms governing the dialog between HIF-1α and FGF2 to find new molecular triggers of tumour angiogenesis." (PMID 18728783, 2008). "Next, the basal and FGF-2 induced invasion capacity of tumor cells was analyzed." (PMID 15817123, 2005). "We hypothesise that the apparent increase in FGF-2 levels in vivo results primarily from the presence of a significant fraction of host cells (in particular, macrophages, which may contain high levels of FGF-2) within xenografted clone A neoplasms." (PMID 7599036, 1995). "In sham-injected control tumours, the hypoxic percentage increased from about 14% at day 15 postimplantation, (i.e. when sham- or FGF-2 injections were begun) to about 42% by day 22, and to about 75% at 29 days postimplantation (respective average volumes 220, 910, and 2810 mm3)." (PMID 8398700, 1993). "The observed reduction in cancer cell motility upon FGF2 treatment in vitro, together with its expression pattern, supports a potential tumor-suppressive role and suggests that FGF2 may serve as a candidate non-invasive biomarker for monitoring LUAD metastasis." (PMID 41594226, 2026). "Moreover, both factors are so interdependent that overexpression of FGF-2 may be responsible for increasing the resistance of the tumor to therapy directed against VEGF-A." (PMID 38473833, 2024). "Moreover, it secreted VEGF, ANGPT1, and FGF-2 to facilitate angiogenesis and tumor invasion." (PMID 38041687, 2024). "In addition, FGF-2 released by leukemic cells may support tumor progression by directly stimulating bone marrow angiogenesis." (PMID 38473833, 2024). "Thus, our findings highlight the emerging complexity of the immune-associated angiogenic drivers in the tumor microenvironment, adding new elements to the already established TAN-derived proangiogenic factors including MMP-9, VEGF, FGF-2, and Bv8/S100 proteins (summarized in a recent review)." (PMID 38329810, 2024). "Consequently, it promotes tumor progression through the axis FGF2/FGFR1." (PMID 36899938, 2023). "Similarly, tumor suppressor miR-497 could impact erlotinib resistance via modulating expression levels of fibroblast growth factor 2 (FGF2) and fibroblast growth factor receptor 1 (FGFR1)." (PMID 37560164, 2023).